IMPDH2 (inosine monophosphate dehydrogenase 2)
Diseases named in the same sentence as IMPDH2 in open-access papers (continued):
Sharing a sentence is not in itself a finding about the gene and the disease.
juvenile-onset dystonia (1 paper, 2021). "Here we report IMPDH2 as a novel disease gene for dominantly inherited juvenile-onset dystonia-tremor disorder." (PMID 34305140, 2021).
Leber congenital amaurosis (1 paper, 2023). Leber congenital amaurosis (LCA) is a retinal dystrophy defined by blindness and responses to electrophysiological stimulation (Ganzfeld electroretinogram (ERG)) below threshold, associated with severe visual impairment within the first year of life. "Like IMPDH2, mutations in the gene for the other human isozyme, IMPDH1, also cause disease, in this case the retinal diseases Leber congenital amaurosis and retinitis pigmentosa." (PMID 37414152, 2023).
Lesch-Nyhan syndrome (1 paper, 2015). Lesch-Nyhan syndrome (LNS) is the most severe form of hypoxanthine-guanine phosphoribosyltransferase (HPRT) deficiency, a hereditary disorder of purine metabolism, and is associated with uric acid overproduction (UAO), neurological troubles, and behavioral problems. "Immediately downstream of IMPDH, hypoxanthine phosphoribosyltransferase (HPRT) that also showed circadian expression similar to IMPDH2 in our study is implicated in Lesch-Nyhan syndrome, a neurological disease." (PMID 25714999, 2015).
leukopenia (1 paper, 2020). "IMPDH2 and MTHFD1 are involved in nucleic acid metabolism and are responsible for perm reduction and leukopenia." (PMID 32362827, 2020).
lymph node metastasis (1 paper, 2018). "Interestingly, compared with those who had no lymph node metastasis, patients with lymph node metastasis had higher mRNA level of IMPDH2 in CRC tissues (P < 0.05)." (PMID 30518405, 2018).
metastatic disease (1 paper, 2025). "Interestingly, elevated IMPDH2 expression can serve as an independent prognostic biomarker for poor NPC prognosis in patients with localized or advanced metastatic disease." (PMID 40367275, 2025).
Obesity (1 paper, 2017). Accumulation of substantial excess body fat. "Downregulation of monocyte IMPDH2 (β = −0.496, p = 0.004) and TMEM134 (β = −0.314, p = 0.043) was associated with obesity in adults (BMI >30 kg/m2), paralleling our findings in children." (PMID 29203885, 2017). "Our study showed a distinctive monocyte gene expression profile in childhood obesity, and downregulation of monocyte IMPDH2 and TMEM134 was also associated with obesity in the adult cohort at risk." (PMID 29203885, 2017).
Parkinson disease (1 paper, 2023). A progressive degenerative disorder of the central nervous system characterized by loss of dopamine producing neurons in the substantia nigra and the presence of Lewy bodies in the substantia nigra and locus coeruleus. "Impdh2 has been shown to have high affinity to Park2, mutations in which are a major cause of early onset Parkinson’s disease, a progressive neurodegenerative disorder characterized by a selective loss of dopaminergic neurons." (PMID 37958822, 2023).
Rotavirus infection (1 paper, 2022). Infection with any of the rotaviruses. "In an earlier study, RIB (the IMPDH2 inhibitor) decreased the IL-6/IL-8 secretion in the animal models of rotavirus infection." (PMID 36177032, 2022).
sarcoma (1 paper, 2026). A usually aggressive malignant neoplasm of the soft tissue or bone. "Gene expression data, as well as clinical outcomes for sarcoma patients, from The Cancer Genome Atlas (TCGA) were analyzed to determine the association between IMPDH2 expression and survival." (PMID 41522344, 2026). "Although this trend was not statistically significant (log-rank p = 0.061), it suggests that higher expression of IMPDH2 may be associated with decreased survival of patients with sarcoma." (PMID 41522344, 2026). "Our findings from the TCGA cohort reveal that elevated expression of IMPDH2 correlates with a trend toward reduced OS in patients with sarcoma." (PMID 41522344, 2026). "To further investigate the role of IMPDH2 in sarcoma, we analyzed its expression levels in tumor tissues and compared them with those in normal tissues." (PMID 41522344, 2026). "Differential expression analyses further highlighted marked overexpression of IMPDH2 in sarcoma tissues compared with normal tissues." (PMID 41522344, 2026). "This overexpression suggests a potential role for IMPDH2 in sarcoma pathogenesis, potentially by supporting the increased nucleotide synthesis required for rapid cell proliferation of malignant cells." (PMID 41522344, 2026). "The presence of IMPDH2 in these sarcoma cell lines supports its relevance to this cancer type, and underscores its potential as a therapeutic target." (PMID 41522344, 2026). "Additional in vitro and in vivo studies are warranted to assess the effects of IMPDH2 inhibition on sarcoma cell viability and tumor growth, as well as to evaluate potential resistance mechanisms." (PMID 41522344, 2026). "Our results indicate a clear trend: sarcoma patients with elevated levels of IMPDH2 expression have lower survival rates, reinforcing the enzyme's potential as a therapeutic target." (PMID 41522344, 2026). "To assess the prognostic relevance of IMPDH2 expression in sarcoma, we performed a Kaplan-Meier survival analysis using data from TCGA cohort." (PMID 41522344, 2026). "Sarcoma patients with high expression of IMPDH2 showed a trend towards poorer overall survival." (PMID 41522344, 2026). "For example, IMPDH2 inhibitors could be explored as adjunct therapies for sarcoma treatment." (PMID 41522344, 2026).
steatosis (1 paper, 2016). Increased lipid within the cytoplasm of cells. "Alteration in CCR7, IMPDH2, IL6ST, MYC, LPIN1, PDE7A and RORA was significantly associated with hepatotoxicity including liver damage, -hyperplasia, -inflammation, -steatosis, -fibrosis, -necrosis and -proliferation." (PMID 26907258, 2016).
viral infection (1 paper, 2022). "Overall, our results identify a novel role of SARS-CoV-2 Nsp14 in inducing NF-κB activation through IMPDH2 to promote viral infection." (PMID 36177032, 2022). "The antiviral effect of IMPDH2 inhibitors is likely through inhibition of NF-κB, supported by our results showing that NF-κB inhibitors, particularly bortezomib, indeed restrict viral infection of SARS-CoV-2 in cell culture as well." (PMID 36177032, 2022). "We next tested whether IMPDH2 inhibitors (RIB, MPA) impact SARS-CoV-2 infection in vitro, considering that virus-mediated NF-κB activation modulates viral infection." (PMID 36177032, 2022).
cancer (41 papers, 2010 to 2026). A tumor composed of atypical neoplastic, often pleomorphic cells that invade other tissues. "The proliferative demands of cancer cells necessitate an increased supply of these nucleotides, underlining the critical role of IMPDH2 in cell growth and replication." (PMID 41522344, 2026). "Inosine monophosphate dehydrogenase 2 (IMPDH2) is implicated in survival and proliferation of cancer cells because of its role in guanine nucleotide biosynthesis." (PMID 41522344, 2026). "By using this strategy, we introduced a point mutation at residue 12 of IMPDH2 in various cancer cell lines, effectively preventing IMPDH polymerisation and cytoophidium assembly." (PMID 40186514, 2025). "Utilising the ABEmax base editor, we introduced a Y12C point mutation into IMPDH2 across multiple cancer cell lines." (PMID 40186514, 2025). "In this study, a Y12C mutation in IMPDH2 was introduced via ABEmax base‐editing in human cancer cell lines to disrupt IMPDH polymerisation." (PMID 40186514, 2025). "While Inosine Monophosphate Dehydrogenase 2(IMPDH2) has been associated with cancer progression, its specific role and clinical implications in HB have not been fully elucidated." (PMID 39085725, 2024). "A recent study found that nucleolar hypertrophy, which is caused by the induction of the IMPDH2 gene, is required for the efficient promotion of growth in cancers." (PMID 37409959, 2023). "As for the role of IMDPH in tumors, recent studies have shown that high IMPDH2 expression was associated with cancer progression." (PMID 36711025, 2023). "High levels of guanosine triphosphate (GTP) synthesis are associated with cancer produced by inosine monophosphate dehydrogenase-2 (IMPDH2)." (PMID 37215921, 2023). "Especially, the expression and activity of IMPDH2 are upregulated in various tumors, which are associated with aggressiveness in several experimental cancer models, and poor clinical outcome." (PMID 35403278, 2022). "Accumulating evidence reveals that IMPDH2 was significantly elevated in multiple types of tumor cells and associated with cancer progression and poor prognosis of tumor patients." (PMID 30518405, 2018). "Numerous studies have shown that high IMPDH2 expression is associated with tumorigenesis and progression in most cancers, indicating that IMPDH2 may be a significant biomarker." (PMID 38310229, 2024). "In addition, significantly higher levels of serum IMPDH2 were detected in cancer patients with GS ≥ 8 vs. GS < 8, and also associated with metastasis." (PMID 30158500, 2018). "Elevated IMPDH2 activity supports a heightened proliferative rate and increased survival capabilities of cancer cells, thereby contributing to tumor progression and poor clinical outcomes." (PMID 41522344, 2026). "A growing body of research demonstrates a correlation between elevated expression of IMPDH2 and the aggressiveness of various cancers, including leukemia, lymphoma, and several solid tumors 14-16." (PMID 41522344, 2026). "This association has been noted particularly in studies showing that cancer cells often upregulate IMPDH2 as a compensatory mechanism to meet their increased metabolic demands, highlighting its potential as a therapeutic target 12-16." (PMID 41522344, 2026). "Although IMPDH1 and IMPDH2 share 84% amino acid identity and have nearly identical kinetic properties in vitro, IMPDH2 tends to be specifically upregulated in cancer." (PMID 40491496, 2025). "By introducing the Y12C mutation to endogenous IMPDH2, we assess the importance of IMPDH polymerisation and cytoophidium formation in multiple cancer cell lines both in vitro and in vivo." (PMID 40186514, 2025). "We show that phosphorylation at the conserved Y233 residue within the IMPDH2 allosteric domain controls its enzymatic activity, directly linking TK signaling to metabolic reprogramming in cancer." (PMID 41154443, 2025).
cancer (continued). "Inosine 5′-monophosphate dehydrogenase 2 (IMPDH2) is an enzyme that regulate the speed of de novo guanine nucleotide synthesis and therefore considered a potential target for cancer therapeutics due to its consistent overexpression in various TNBCs." (PMID 40689201, 2025). "RNA-seq data from the Human Protein Atlas reveal widespread IMPDH2 overexpression compared to IMPDH1 across many cancer cell lines." (PMID 41154443, 2025). "We show that phosphorylation at the conserved Y233 residue within the allosteric domain enhances IMPDH2 activity, linking TK signaling to metabolic reprogramming in cancer cells." (PMID 41154443, 2025). "Positive results from these studies would have profound implications for the repurposing of IMPDH2 inhibitors in cancer therapy." (PMID 39774345, 2025). "In contrast to other cancer models, inhibition of IMPDH2 in MCC led to rapid ablation of nascent DNA synthesis and the onset of replication stress without a significant effect on total or ribosomal RNA biosynthesis." (PMID 40491496, 2025). "While IMPDH2 overexpression is common in cancers, the functional significance of its phosphorylation has largely remained unexplored." (PMID 41154443, 2025). "In contrast, IMPDH2 manifests significantly heightened expression levels across various malignant tumors." (PMID 39085725, 2024). "Our findings substantiate an expanding body of literature indicating IMPDH2 involvement across diverse cancer types." (PMID 39085725, 2024). "The removal of B7-H3 from cancer cells in 2D results in sensitisation to chemotherapeutic stress and reduces cell viability in an IMPDH2-dependent manner." (PMID 37444640, 2023). "In summary, our study provides new evidence that B7-H3 is associated with one of the key rate-limiting metabolic enzymes IMPDH2, and this complex localises to intracellular RRs in normal epithelia and the plasma membrane in cancer cells that overexpress B7-H3." (PMID 37444640, 2023). "In support of this, IMPDH2 has recently been shown to localise to the plasma membrane of cancer cells and control local GTP synthesis to support actin reorganisation." (PMID 37444640, 2023). "Here, we show that B7-H3 forms a complex with the metabolic enzyme IMPDH2, and this protects cancer cells from oxidative stress and resulting apoptosis triggered by chemotherapy." (PMID 37444640, 2023). "The IMPDH2:B7-H3 complex provides a protective role in cancer cells to promote cell survival through the maintenance of downstream metabolic activity and oxidative stress." (PMID 37444640, 2023). "Mechanistically, the IMPDH2:B7-H3 complex provides a protective role in cancer cells to escape oxidative stress triggered by chemotherapy, thus leading to cell survival." (PMID 37444640, 2023). "The abnormally increased activity makes IMPDH, especially IMPDH2, a new target for anti-cancer drug development." (PMID 35964092, 2022). "Expression of IMPDH2 is enhanced significantly in rapidly proliferating cells including various types of cancers including colorectal, bladder, prostate, kidney, nasopharyngeal carcinoma and leukemia." (PMID 34035425, 2021). "Here, using evidence from computer modeling, deletion analysis, reciprocal immunoprecipitation, and PLA, we revealed that RAC1 directly interacts with IMPDH2, recruiting it to cell membrane protrusions that are pivotal for cancer cell invasion." (PMID 34667203, 2021). "There are two isotypes of IMPDH in humans, IMPDH isotype 1 (IMPDH1) and IMPDH isotype 2 (IMPDH2), of which IMPDH2 has been reported to be more highly upregulated in cancers." (PMID 33224873, 2020). "IMPDH2 is believed to be a fascinating target for cancer therapy due to its overexpression particularly in rapidly proliferating and neoplastic cells." (PMID 30518405, 2018). "Inosine 5′-monophosphate dehydrogenase type II (IMPDH2) was originally identified as an oncogene in several human cancers." (PMID 30518405, 2018).
cancer (continued). "In mammalian cells, mainly in cancer cell lines, some RR structures also contain inosine monophosphate dehydrogenase 2 (IMPDH2) as a major component." (PMID 29623259, 2018). "CTPS1 enzyme inhibitors 6-diazo-5-oxo-L-norleucine and Acivicin as well as the IMPDH2 inhibitor Ribavirin exhibited dose-dependent induction of RR in >95% of cells in all cancer cell lines tested as well as mouse primary cells." (PMID 22220215, 2011). "Expression of IMPDH, particularly the type II isoform, has been shown to be significantly increased in many types of malignancies, making IMPDH2 also an attractive target for cancer therapy." (PMID 20808934, 2010). "Because IMPDH2 is a key enzyme in the de novo guanine nucleotide synthesis pathway 13, 24, its upregulation could provide a metabolic advantage to cancer cells, thereby facilitating growth and survival." (PMID 41522344, 2026). "Thus, more comprehensive evaluations of the effects of IMPDH2 inhibition in cancer with these drugs are needed." (PMID 39774345, 2025). "Consistently, IMPDH2 levels could discriminate the survival of adjuvant and neoadjuvant chemotherapy-treated TNBC patients, suggesting that IMPDH2 induction could be a means for cancer cells to survive/escape therapy." (PMID 39774345, 2025). "IMPDH1 is constantly expressed, while IMPDH2 is inducible and frequently overexpressed in cancer." (PMID 41154443, 2025). "Given the role of tyrosine phosphorylation in regulating metabolic enzymes in tyrosine kinase-driven cancers, we investigated whether oncogenic kinases phosphorylate IMPDH2." (PMID 41154443, 2025). "The IMPDH2 Y12C mutation does not induce significant cell toxicity or growth defects in cancer cell lines in vitro." (PMID 38717553, 2024). "Furthermore, elevated IMPDH2 levels have demonstrated suppression of cancer cell apoptosis through the regulation of multifaceted pathways, including the PI3K/AKT/mTOR and PI3K/c-Myc/AFF4 pathways." (PMID 39085725, 2024). "Interestingly, PD-L1 has been reported to mediate cancer cell intrinsic functions in cold tumours through mTOR activation, and IMPDH2 promotes proliferation and migration through mTOR activation, suggested to be downstream of B7-H3." (PMID 37444640, 2023). "It was found that one of the isoforms of IMPDH, IMPDH1, may be expressed in both normal and cancer cells, but IMPDH2 is expressed preferably in cancer-transformed cells." (PMID 37175852, 2023). "Overexpression of IMPDH2 elevates IMP or GMP intensity in cancer patients." (PMID 37215921, 2023). "Given that B7-H3 colocalised with IMPDH2 in RRs in epithelial cells and in the membrane in cancer cells, we next sought to determine whether these two proteins form part of the same biochemical complex." (PMID 37444640, 2023). "Increased IMPDH2 expression is present in various human cancers and may be related to a poor prognosis." (PMID 37409959, 2023). "However, B7-H3 depletion reduces the formation of IMPDH2 containing RRs in the presence of MPA in cancer cells, indicating that B7-H3 plays a key role in the control of RRs, and therefore potentially in IMPDH2 activation status, under stress conditions." (PMID 37444640, 2023). "IMPDH2 expression is also an independent prognostic biomarker for other cancer types." (PMID 34035425, 2021). "Moreover, some PCGs, such as IMPDH2, RRM2, and PAICS, involved in this subpathway region are closely associated with colorectal or other types of cancer." (PMID 28152521, 2017). "Studies have demonstrated that CTPS1 and IMPDH2 are aberrantly expressed in different cancers." (PMID 22220215, 2011). "Besides, four sex-biased exon skipping events in cancer therapeutic target genes (FDPS, FGFR1, CDK4, and IMPDH2) could cause the loss of partial protein function, which may contribute to a differential drug response rate in male and female patients." (PMID 39175079, 2024).